PSMB2 (proteasome 20S subunit beta 2)
Description:
Non-catalytic component of the 20S core proteasome complex involved in the proteolytic degradation of most intracellular proteins. This complex plays numerous essential roles within the cell by associating with different regulatory particles. Associated with two 19S regulatory particles, forms the 26S proteasome and thus participates in the ATP-dependent degradation of ubiquitinated proteins. The 26S proteasome plays a key role in the maintenance of protein homeostasis by removing misfolded or damaged proteins that could impair cellular functions, and by removing proteins whose functions are no longer required. Associated with the PA200 or PA28, the 20S proteasome mediates ubiquitin-independent protein degradation. This type of proteolysis is required in several pathways including spermatogenesis (20S-PA200 complex) or generation of a subset of MHC class I-presented antigenic peptides (20S-PA28 complex).
Synonyms: HC7-I
Tractability: Small molecule: an approved drug acts on it; a structure with a bound ligand is known; a high-quality ligand is known; it belongs to a druggable protein family. PROTAC: ubiquitination databases record sites on it; its protein half-life has been measured; a small molecule that binds it is known.
Target class: Threonine protease; Protease; Threonine protease T1A subfamily; Threonine protease PBT clan; Enzyme
Chemical probes: CHEMBL2326261
Gene: Protein-coding gene on chromosome 1 (35,599,541 to 35,641,526, reverse strand). Ensembl gene ENSG00000126067.
Subcellular location: Cytoplasm; Nucleus
Subcellular location (Human Protein Atlas): Nucleoplasm
Pathways (Reactome):
Immune System: AMPK-induced ERAD and lysosome mediated degradation of PD-L1(CD274); Activation of NF-kappaB in B cells; Antigen processing: Ub, ATP-independent proteasomal degradation; Antigen processing: Ubiquitination & Proteasome degradation; CLEC7A (Dectin-1) signaling; Cross-presentation of soluble exogenous antigens (endosomes); Dectin-1 mediated noncanonical NF-kB signaling; Downstream TCR signaling; ER-Phagosome pathway; FCERI mediated NF-kB activation; GSK3B-mediated proteasomal degradation of PD-L1(CD274); Interleukin-1 signaling; NIK-->noncanonical NF-kB signaling; SPOP-mediated proteasomal degradation of PD-L1(CD274); TNFR2 non-canonical NF-kB pathway
Cell Cycle: APC/C:Cdc20 mediated degradation of Securin; APC/C:Cdh1 mediated degradation of Cdc20 and other APC/C:Cdh1 targeted proteins in late mitosis/early G1; Autodegradation of Cdh1 by Cdh1:APC/C; Autodegradation of the E3 ubiquitin ligase COP1; Cdc20:Phospho-APC/C mediated degradation of Cyclin A; FBXL7 down-regulates AURKA during mitotic entry and in early mitosis; G2/M Checkpoints; SCF(Skp2)-mediated degradation of p27/p21; SCF-beta-TrCP mediated degradation of Emi1; Separation of Sister Chromatids; The role of GTSE1 in G2/M progression after G2 checkpoint; Ubiquitin-Mediated Degradation of Phosphorylated Cdc25A; Ubiquitin-dependent degradation of Cyclin D
Signal Transduction: Asymmetric localization of PCP proteins; Degradation of AXIN; Degradation of DVL; Degradation of GLI1 by the proteasome; Degradation of GLI2 by the proteasome; Degradation of beta-catenin by the destruction complex; GLI3 is processed to GLI3R by the proteasome; Hedgehog 'on' state; Hedgehog ligand biogenesis; MAPK6/MAPK4 signaling; Negative regulation of NOTCH4 signaling; Regulation of PTEN stability and activity
and 28 more pathways
Gene Ontology:
Molecular function: protein binding; structural constituent of proteasome
Biological process: proteasomal protein catabolic process; proteasome-mediated ubiquitin-dependent protein catabolic process; regulation of proteasomal protein catabolic process; response to oxidative stress; apoptotic process; CD8-positive, alpha-beta T cell differentiation; CD8-positive, alpha-beta T cell homeostasis; cellular response to type I interferon; DNA damage response; DNA repair; flagellated sperm motility; immune system process; meiotic cell cycle; negative regulation of regulatory T cell differentiation; positive regulation of interleukin-2 production; positive regulation of tumor necrosis factor production; positive regulation of type II interferon production; proteasomal ubiquitin-independent protein catabolic process; regulation of G1/S transition of mitotic cell cycle; response to type II interferon; spermatogenesis; T-helper 1 cell differentiation; T-helper 17 cell differentiation; thymic T cell selection; protein catabolic process
Cellular component: cytoplasm; extracellular exosome; membrane; nucleoplasm; nucleus; proteasome complex; proteasome core complex; cytosol; proteasome core complex, beta-subunit complex; proteasome storage granule; spermatoproteasome complex; synaptic vesicle
Genetic constraint (gnomAD): Loss-of-function variants: 13 observed, 23.55 expected, observed/expected ratio (o/e) 0.55, 90% interval 0.36 to 0.88. The upper end of that interval is the gene's LOEUF score, 0.88, which puts it in group 3 of 6, group 1 being the genes least tolerant of losing a copy. Missense variants: 163 observed, 220.82 expected, observed/expected ratio (o/e) 0.74, 90% interval 0.65 to 0.84. Synonymous variants: 73 observed, 80.61 expected, observed/expected ratio (o/e) 0.91, 90% interval 0.75 to 1.1.
Homologues: Orthologues: chimpanzee PSMB2 (100% identical), macaque PSMB2 (100% identical), dog PSMB2 (99% identical), pig PSMB2 (99% identical), rabbit PSMB2 (99% identical), guinea pig PSMB2 (99% identical), mouse Psmb2 (97% identical), rat Psmb2 (96% identical), zebrafish psmb2 (81% identical), tropical clawed frog psmb2 (81% identical), Drosophila melanogaster Prosbeta4 (50% identical), Drosophila melanogaster Prosbeta4R2 (43% identical), and 2 more. Paralogues in human: PSMB1 (23% identical), PSMB9 (23% identical), PSMB10 (23% identical), PSMB8 (22% identical), PSMB11 (21% identical), PSMB5 (21% identical), PSMB7 (21% identical), PSMA4 (21% identical), PSMB3 (19% identical), PSMA1 (19% identical), PSMA5 (19% identical), PSMA6 (19% identical), and 6 more.
Diseases named in the same sentence as PSMB2 in open-access papers:
PSMB2 is named in the same sentence as 40 diseases in open-access papers, as found by Europe PMC text mining. Sharing a sentence is not in itself a finding about the gene and the disease. The quoted sentences say what the papers report.
glioma (8 papers, 2022 to 2025). A benign or malignant brain and spinal cord tumor that arises from glial cells (astrocytes, oligodendrocytes, ependymal cells). "PSMB2 also acts as an oncogene in glioma and is associated with the immune microenvironment." (PMID 41444773, 2025). "PSMB2 mRNA is overexpressed in glioma, and high PSMB2 mRNA is associated with prognosis and OS." (PMID 38467767, 2024). "In human glioma tissue, expression of another member of this family, PSMB2, is higher compared to normal brain and correlates with poor prognosis and high tumor grade." (PMID 42135822, 2025). "TCGA database help us to estimate the glioma patient’s expression difference, prognostic value, and biology of PSMB2." (PMID 38467767, 2024). "This study attempted to reveal the function of the proliferation and invasion of glioma cells, which is affected by proteasome 20S subunit beta 2 (PSMB2)." (PMID 38467767, 2024). "The PSMB2 RNA and protein expression in glioma patients was tested by quantitative PCR and Western blotting." (PMID 38467767, 2024). "Next, to comprehend the contribution of PSMB2 in the glioma pathologic process, we used Gene Ontology (GO) to obtain the cell function." (PMID 38467767, 2024). "The majority of studies have shown that various tumors, including glioma, consider PSMB2 expression an important biomarker for poor prognoses." (PMID 38467767, 2024). "We detected the PSMB2 expression level in glioma tissues, 33 glioma tissue specimens (including 14 WHO grade II specimens and 19 WHO grade III-IV specimens) and 4 normal tissue specimens were collected." (PMID 38467767, 2024). "PSMB2 was considered an independent prognostic factor for OS in glioma through multivariate analysis (HR = 2.807, 95% CI 1.484–5.310, P = 0.002)." (PMID 38467767, 2024). "We found that PSMB2 was overexpressed in multiple malignant tumors in the TCGA database; PSMB2 expression was significantly different between low-grade gliomas and glioblastomas." (PMID 38467767, 2024). "PSMB2 protein expression in gliomas was detected by WB, and PSMB2 protein expression in high-grade gliomas was significantly higher than that in low-grade gliomas and normal tissues." (PMID 38467767, 2024). "PSMB2 expression was higher in glioma tissues, and its expression positively correlated with poor prognosis and high tumor grade and after PSMB2 knockdown, the proliferation, invasion and migration of glioma cells were weakened." (PMID 38467767, 2024). "We also evaluated PSMB2 and the response to temozolomide or cisplatin which are commonly used in glioma, and the lower the expression of PSMB2 was, the higher the IC50 values of temozolomide and cisplatin." (PMID 38467767, 2024). "By analyzing glioma patients’ RNA sequencing data and the clinical outcome data which was downloaded from the TCGA database, we found that PSMB2 was overexpressed in glioma, and PSMB2 expression in glioma increased with increasing tumor malignancy." (PMID 38467767, 2024). "To further elucidate the role of PSMB2 in glioma, we also evaluated immune checkpoint differences between PSMB2 in two subgroups." (PMID 38467767, 2024). "Then, we showed that PSMB2 is highly expressed not only in glioma but also in various tumors through TCGA dataset analysis." (PMID 38467767, 2024). "PSMB2 expression in glioma cells was significantly higher than that in normal brain cells." (PMID 38467767, 2024). "PSMB2 may be engaged in the pathogenesis of glioma, and PSMB2 may play a potential role as a clinical immunotherapeutic target that was not shown in a previous study." (PMID 38467767, 2024). "We detect the changes in the proliferation, invasion and migration of glioma cells by plate colony formation assay, transwell assay, wound healing assay and flow cytometry and PSMB2 expression was verified by quantitative PCR and Western blotting to identify the mRNA and protein levels." (PMID 38467767, 2024).
glioma (continued). "In addition, in TCGA database and CGGA database, the expression of PSMB2 was different in different grades of glioma, and its expression increased with increasing malignant degree of the tumor." (PMID 38467767, 2024). "Therefore, we analyzed several databases to reveal its role in tumors, which will help us to find a potential immunotherapeutic target, suggesting that PSMB2 is a therapeutic target to alter the progression of glioma." (PMID 38467767, 2024). "PSMB2 was suggested as a special prognostic factor for glioma." (PMID 38467767, 2024). "It was suggested that high expression of PSMB2 in glioma patients may lead to a better response to temozolomide and cisplatin." (PMID 38467767, 2024). "In this study, we found that PSMB2 was overexpressed in glioma patients along with significantly increased infiltration of Th2 cells; consequently, PSMB2 may participate in mediating immune escape in glioma cells." (PMID 38467767, 2024). "PSMB2 has great potential for the prognosis of glioma and may be a new target for glioma immunotherapy." (PMID 38467767, 2024). "In our analysis, we found that PSMB2 was positively correlated with the malignancy degree of glioma, and it may be highly correlated with the immunity of glioma, indicating its main mechanism." (PMID 38467767, 2024). "In multiple biological processes of glioma, PSMB2 induced the occurrence and development of glioma." (PMID 38467767, 2024). "To further understand the role of PSMB2 in glioma patients, we performed KEGG and GO analyses." (PMID 38467767, 2024). "In conclusion, PSMB2 is expected to be a new focus for glioma immunotherapy." (PMID 38467767, 2024). "In addition, PSMB2 is a member of proteasome 20S core beta subunit, which plays several roles in many types of cancers, such as gastric cancer or glioma." (PMID 37958632, 2023). "Moreover, we found that the higher PSMB2 expression was, the shorter the OS of glioma patients." (PMID 38467767, 2024). "Therefore, we speculate that the overexpression of PSMB2 can accelerate the degradation of tumor suppressor genes, stabilize the internal environment, promote the proliferation of glioma cells, increase migration and invasion, and inhibit apoptosis." (PMID 38467767, 2024). "Therefore, PSMB2 expression may be a better predictor of glioma patient 1/3/5-year prognosis." (PMID 38467767, 2024). "Overexpression of the genes whose transcripts act as potential targets fordysregulated miRNAs in the IDHmut and IDHwt groups is observed in moreaggressive glioma types: FKBP9 – CREB3L4, MCM4, MCM6, PSMB2, ARID1A, ARL4C, GRPEL2, and C9orf64." (PMID 39539523, 2024). "We performed qRT-PCR analysis and found that the expressions of TNFAIP6, PSMB2, IRF4 and IFNAR2 were significantly upregulated in glioma tissues (n = 30) compared to normal brain tissues (n = 10)." (PMID 36712869, 2022). "Although this study obtained a deeper understanding of the linkage between PSMB2 and glioma, the role of PSMB2 in glioma progression has not yet been reported." (PMID 38467767, 2024).
hepatocellular carcinoma (4 papers, 2019 to 2022). A malignant tumor that arises from hepatocytes. "For example, in hepatocellular carcinoma, downregulation of CFIm25 subunit of cleavage factor results in high expression of PSMB2 and CXXC5 by increasing the usage of the proximal polyadenylation site." (PMID 31039132, 2019). "Aberrant expression of members of the proteasome subunit beta (PSMB) family (including PSMB2, PSMB4, PSMB7 and PSMB8) has been reported in hepatocellular carcinoma (HCC)." (PMID 36062301, 2022). "PSMB2 overexpression is an oncogenic event in many kinds of malignancies, such as ovarian cancer, chronic myelogenous leukemia (CML), osteosarcoma, hepatocellular carcinoma (HCC) 22, 46-48." (PMID 35693739, 2022).
Sepsis (3 papers, 2017 to 2026). Sepsis is defined as life-threatening organ dysfunction caused by a dysregulated host response to infection. "In sepsis patients, higher plasma levels of PSMA7 and PSMB2 were associated with increased 90-day mortality and positively correlated with markers of liver injury and SOFA scores." (PMID 41939900, 2026). "MICB, PSMB2, PSMB8 and PSME2 showed consistently low level of expression in melioidosis cohort irrespective of other factors like comorbidities (risk factors), duration of clinical symptoms and antibiotic treatment, compared to other sepsis controls." (PMID 28628607, 2017). "MICB, PSMB2, PSMB8 and PSME2 were significantly up regulated in other sepsis cases compared to healthy controls while these target genes showed no significant differential expression in patients suffering from melioidosis compared to healthy controls." (PMID 28628607, 2017).
breast carcinoma (2 papers, 2016 to 2019). "Moreover, breast cancer patients with tumors exhibiting the lowest quartile of PSMB2 and PSMB5 combined mRNA expression showed reduced 5-year survival compared to patients with tumors in the highest quartile." (PMID 26930717, 2016). "For module #35, while most of the genes locate on 1q34, many of the genes such as UQCRH, PSMB2, PPIH, and YBX1 are involved in RNA processing and have been identified with breast cancer in multiple studies." (PMID 30906311, 2019).
COVID-19 (2 papers, 2022 to 2024). A disease caused by infection with severe acute respiratory syndrome coronavirus 2. "Regarding the expression of 20S subunits in the α- and β-ring the mRNA expression of PSMA4, PSMA5, PSMB2, PSMB9, PSMB10 significantly increased in COVID-19 patients (COV) when compared to healthy control (HC)." (PMID 35327634, 2022).
prostate carcinoma (2 papers, 2020 to 2022). A carcinoma that arises from epithelial cells of the prostate gland. "On the other hand, higher expression levels of PSMB2 were correlated with poor OS in patients with kidney, liver, and prostate cancers, whereas lower levels of PSMB2 were correlated with poor OS in patients with bladder and lung cancers." (PMID 32933107, 2020). "Overall, these data are consistent with the significant correlation found between the combined gene expression of GPX2, EP300, and PSMB2, and OS in prostate cancer patients." (PMID 32933107, 2020). "Moreover, SRPK2 and PSMB2 over-expression was observed in prostate cancer, and correlated with a high Gleason score, advanced pathological stage, tumor metastasis, and significantly poor 10-year metastatic rate in prostate cancer, in younger men." (PMID 32933107, 2020). "Then, we evaluated the gene expression profiles for the six HUB nodes (ABL1, EP300, FYN, MYC, PSMB2, and SRPK2) in all the prostate cancer cells, compared to normal prostate EPN cells." (PMID 32933107, 2020).
bladder cancer (1 paper, 2020). "Moreover, in our previous paper, PSMB2 was a HUB node in the bladder cancer network." (PMID 32933107, 2020).
bowel cancer (1 paper, 2022). "However, research on proteasome 20S subunit beta 2 (PSMB2) and aminocarboxymuconate semi-aldehyde decarboxylase (ACMSD) are waiting to be explored in bowel cancer." (PMID 36035152, 2022).
interstitial lung disease (1 paper, 2008). A diverse group of lung diseases that affect the lung parenchyma. "We, therefore, recommend PSMB2 and RPL32 as suitable reference genes for the normalisation of the gene expression in unseparated BAL cells, namely in interstitial lung diseases." (PMID 18671841, 2008). "PSMB2 and RPL32 are, therefore, suitable reference genes to normalize qRT-PCR in BAL cells in sarcoidosis, and other interstitial lung disease." (PMID 18671841, 2008). "We, therefore, suggest that the use of single reference genes PSMB2 or RPL32 is sufficient for normalisation of target gene expression in BAL cells, at least in interstitial lung diseases, where we validated their expression stability in the second, independent BAL cohort." (PMID 18671841, 2008).
invasive breast carcinoma (1 paper, 2016). A carcinoma that infiltrates the breast parenchyma. "Intriguingly, we found that tumor samples from patients with invasive breast carcinoma exhibited significantly lower PSMB2 and PSMB5 proteasome subunit mRNA expression compared to samples derived from normal tissue." (PMID 26930717, 2016).
neuroblastoma (1 paper, 2026). Neuroblastoma (NB) is the most common solid, extracranial childhood tumor. "We validated this model in differentiated SH‐SY5Y neuroblastoma cells CRISPR‐engineered to express PSMB2‐eGFP from the genomic loci and incubated these with aS aggregates." (PMID 41277520, 2026).
renal carcinoma (1 paper, 2022). A carcinoma arising from the epithelium of the renal parenchyma or the renal pelvis. "High PSMB2 expression was also correlated with poor OS in all and RCC patients, indicating its oncogenic role in renal cancer." (PMID 35693739, 2022).
sarcoidosis (1 paper, 2008). Sarcoidosis is a multisystemic disorder of unknown cause characterized by the formation of immune granulomas in involved organs. "Relative mRNA expression levels of INFG were higher in sarcoidosis patients than in control subjects when the normalisation was done with gene PSMB2 (fold change ± SD: 2.56 ± 1.62; p = 0.004), with gene RPL32 (2.58 ± 1.46; p = 0.004), and with gene pair PSMB2-RPL32 (2.44 ± 1.20; p = 0.02)." (PMID 18671841, 2008). "Finally, to demonstrate effect of traditional (ACTB/GAPDH) and novel (PSMB2/RPL32) reference genes as denominators, expression of two cytokines known associated with sarcoidosis was investigated in sarcoid BAL cells." (PMID 18671841, 2008). "The stability of mRNA expression of PSMB2 and RPL32 genes was further validated in the second, independent BAL cohort of sixty-three sarcoidosis patients and seventeen control subjects." (PMID 18671841, 2008).